HOXB13 (homeobox B13)
Diseases named in the same sentence as HOXB13 in open-access papers (continued):
Sharing a sentence is not in itself a finding about the gene and the disease.
prostate carcinoma (continued). "Furthermore, we demonstrated that the HOXB13/HOXA11-AS axis regulated IBSP promoter and integrin subunits specific to prostate cancer bone metastasis." (PMID 33514011, 2021). "We compared the expression levels of eight integrin subunits (ITGA2, ITGA5, ITGAV, ITGB1, ITGB3, ITGB4, ITGB5, and ITGB6), HOXB13, HOXA11-AS, CCL2, CXCL12, and IBSP in prostate cancer tissues that had metastasized to bone, lymph nodes, lungs, liver, and other organs." (PMID 33514011, 2021). "In addition, in prostatic cancer tissues, statistically significant positive correlations between MYC and HOXB13 mRNA levels was observed, while an independent group confirmed that the tumor-suppressive activity of MEIS1 was dependent on HOXB13." (PMID 34698191, 2021). "Finally, we show in laser capture microdissected human prostate cancer samples and the prostate TCGA cohort that MEIS1 expression is inversely proportional to AR activity as well as HOXB13, a known interacting protein of both AR and MEIS1." (PMID 32681068, 2020). "Here, we report a phenotypic and mechanistic determination that MEIS proteins promote indolent and non-metastatic prostate cancer via the HOXB13-dependent regulation of extracellular proteoglycans, in particular the multi-RTK inhibitor Decorin." (PMID 32553107, 2020). "Interestingly, at the reprogrammed AR binding sites in human prostate cancer cells it was reported the colocalized binding of FOXA1 and HOXB13—two prostate master transcription factors." (PMID 31366128, 2019). "The homeobox B13 (HOXB13) gene is involved in prostate development, and in vitro results have suggested that its transcription factor is involved in prostate cancer (PCa) cell growth through androgen receptor interaction, regulation by FOXA1, and other pathways." (PMID 30527799, 2019). "Despite these findings, differential HoxB13 expression according to histologic subtype and the clinical implications of Hox expression in prostate cancer have not been fully investigated." (PMID 31882852, 2019). "In conclusion, to our knowledge, this is the first study to rigorously compare the prevalence of the most common molecular subtypes of primary prostate cancer between HOXB13 G84E carriers and non-carriers, matched for relevant clinical-pathologic variables." (PMID 28186998, 2017). "In the NCI-H660, DU145 and PNT2 cell lines no HOXB13 was detected, in opposition to the other prostate cancer cell lines, with MDA-PCa-2b being the one with the highest expression levels." (PMID 28050579, 2016). "For prostate cancer, we analyzed 5 genes and did not observe an over-representation of SNP associations at p<0.05 (observed/tested: BRCA2, 2/83; ELAC2, 1/9, HOXB13, 0/2; MSR1, 1/22; RNASEL, 2/21)." (PMID 23555315, 2013). "In line with these previous data, results from this study demonstrated that ATRA was able to induce growth arrest of two AR− prostate cancer cells DU145 and PC-3 in a dose-dependent manner, and this effect was partially achieved through promoting HOXB13 mRNA and protein production." (PMID 22808286, 2012). "Noticeably, treatment of AR− prostate cancer cells with ATRA did not change the expressions of HOXB13, EZH2 and DNMT3b at mRNA level, implicating a different mechanism of ATRA action in this particular cell background." (PMID 22808286, 2012). "HOXB13, silenced in androgen receptor-negative (AR−) prostate cancer cells, plays a role in AR− prostate cancer cell growth arrest." (PMID 22808286, 2012). "All CRC cells did not express significant amounts of HOXB13 compared to normal rectum and LNCaP prostate cancer cell." (PMID 15928669, 2005). "Based on these studies HOXB13 removal would not be predicted to be involved in prostate cancer development." (PMID 15583692, 2005). "Interestingly HOXB13 is located at chromosome band 17q21 immediately adjacent to the PRAC and PRAC2 genes, which have also been proposed as markers of human prostate cancer." (PMID 15583692, 2005).
prostate carcinoma (continued). "Aberrant transcription in prostate cancer is not driven solely by AR activity but through the collaborative action of AR enhancers like those of HOXB13 and FOXA1 genes, which modify chromatin structure to facilitate AR and other factors in accessing cancer-specific binding sites." (PMID 39796635, 2024). "We found that HOXB13 mRNA was up-regulated in SLC12A5-overexpressing 22RV-1 cells and this upregulation was partially abrogated by knocking down YTHDC1 in the SLC12A5-overexpressing 22RV-1 cells, suggesting that HOXB13 was the target gene of SLC12A5/YTHDC1 complex in prostate cancer." (PMID 36609444, 2023). "Thus, we performed qPCR analysis of IBSP expression in PC3 cells transfected with siRNA targeting HOXB13 or HOXA11-AS to investigate whether HOXB13 and HOXA11-AS regulate IBSP expression in prostate cancer." (PMID 33514011, 2021). "YY1 and HDAC4 complex represses HOXB13 gene in AR negative prostate cancer cells." (PMID 31824839, 2019). "Transcriptional repression of HOXB13 in AR negative prostate cancer cells." (PMID 31824839, 2019). "In earlier studies, using the same large prostate cancer cohort we had described other very strong and often independent prognostic features such as for example ß3-tubulin, CD57, DAXX, HOXB13, KPNA2, RBM3, mTOR, p62, and TYMS, that might also be worth testing in multiparametric prognostic kits." (PMID 28415558, 2017). "Furthermore, our ChIP assays revealed that EZH2 was able to directly bind onto the HOXB13 promoter, and this may be a silencing mechanism of HOXB13 in the DU145 malignant prostate cancer cells." (PMID 22808286, 2012). "HOXB13 is silenced in androgen receptor-negative (AR−) prostate cancer cells." (PMID 22808286, 2012).
breast carcinoma (48 papers, 2005 to 2025). "This variant correlated with a history of prostate and breast cancers within families, highlighting the potential role of HOXB13 mutations in hereditary PC risk across different populations." (PMID 39606519, 2024). "In breast cancer, high levels of homeobox protein Hox-B13 (HOXB13) have been associated with disease progression of ER-positive breast cancer patients and resistance to tamoxifen treatment." (PMID 32546843, 2020). "The current study is by far the largest study that has been performed evaluating the association with an increased breast cancer risk for germline HOXB13 mutation carriers." (PMID 32546843, 2020). "To date, several studies have investigated the association between the germline HOXB13 p.G84E mutation and breast cancer risk, however, these have led to contradictory results." (PMID 32546843, 2020). "We genotyped four HOXB13 missense mutations: p.G84E, p.P190L, p.R217C and p.R268Q in 68,521 breast cancer cases and 54,865 controls from 81 studies in the BCAC on the OncoArray." (PMID 32546843, 2020). "The tissue microarray analysis revealed a positive association between the expression levels of HBXIP and HOXB13 in ER+ breast cancer patients." (PMID 29471853, 2018). "In ER+ breast cancer, a high expression level of HOXB13 is associated with a more aggressive clinical course." (PMID 29471853, 2018). "Although HOXB13 also plays a role in breast tumor progression, the association of HOXB13 p.G84E with breast cancer risk is less evident." (PMID 27424772, 2016). "A prespecified secondary aim was to similarly examine the extent to which the MGI+HOXB13:IL17BR predicts the risk of breast cancer-specific mortality among tamoxifen-untreated ER-positive, node-negative patients." (PMID 23497539, 2013). "Subsequent studies of the HOXB13:IL17BR index have proven its significance in predicting risk of breast cancer recurrence and tamoxifen response." (PMID 20649975, 2010). "We also performed analyses by receptor status to evaluate whether HOXB13 p.G84E associates with subtype-specific breast cancer risk." (PMID 32546843, 2020). "Therefore, we have genotyped 68,521 breast cancer cases and 54,865 controls from 81 studies in the Breast Cancer Association Consortium (BCAC) for the HOXB13 p.G84E and p.R217C mutations." (PMID 32546843, 2020). "The role of HOXB13 in human cancer has been mostly associated to breast cancer (BC) and PC." (PMID 31137568, 2019). "Considering these observations, HOXB13 might also be a likely candidate for being a breast cancer susceptibility gene." (PMID 27424772, 2016). "In this study, we have explored whether HOXB13 gene mutations are also associated with breast cancer risk." (PMID 27424772, 2016). "A prespecified primary aim was to assess the degree to which the MGI+HOXB13:IL17BR risk classifier predicts the risk of breast cancer-specific mortality among tamoxifen-treated ER-positive, node-negative patients, either alone or after accounting for tumor size and tumor grade." (PMID 23497539, 2013). "The gene encoding HOXB13 maps to chromosome 17q21, a region known to be amplified in breast cancer." (PMID 20649975, 2010). "In this study, we therefore analyzed the entire coding region of the HOXB13 gene in 1,250 Dutch familial breast cancer cases and 800 geographically matched controls to establish whether the p.G84E mutation or other mutations in the HOXB13 gene are associated with an increased breast cancer risk." (PMID 27424772, 2016). "One example of a gene expression-based signature evaluating estrogen signaling is the Breast Cancer Index (HOXB13/IL17BR)." (PMID 38967128, 2024). "Only the Breast Cancer Index (BCI) HOXB13/IL17BR ratio (H/I) has been shown to predict of benefit from endocrine therapy." (PMID 37419892, 2023). "Transient HOXB13 overexpression in breast cancer cells was shown to rapidly reprogram and expand the binding pattern of ER to genomic regions that were previously inaccessible and inactive." (PMID 36527133, 2022).
breast carcinoma (continued). "Due to HOXB13 expression, drug resistance can be seen in some cancers, such as breast cancer and glioblastoma." (PMID 33315534, 2021). "A high HOXB13 to IL17BR expression ratio was associated with a high risk of recurrence and poor outcome for estrogen receptor (ER)-positive breast cancer patients." (PMID 32546843, 2020). "According to a proposed mechanism, HOXB13 binds to the promoter of the inflammatory cytokine interleukin 6 (IL-6) gene to induce its expression in breast cancer cells and exhibit anticancer drug resistance." (PMID 31878059, 2019). "Previous studies have suggested that HOXB13 is involved in the progression of cancer, including prostate, breast cancers, and glioblastoma." (PMID 31878059, 2019). "Here, we were interested in the potential effect of HBXIP, an oncoprotein involved in the acceleration of cancer progression, on the modulation of HOXB13 in TAM resistance of breast cancer." (PMID 29471853, 2018). "Much is disclosed about the important role of HOXB13 in the prediction of TAM therapy, the underlying mechanism of HOXB13 expression regulation in TAM resistance of breast cancer is largely unclear." (PMID 29471853, 2018). "The immunoblotting analysis revealed a positive relationship between HBXIP and HOXB13 in three ER+ breast cancer cell lines, namely MCF-7, T47D, and BT474." (PMID 29471853, 2018). "Previous study found that ALX4 promoted ovarian cancer invasion by forming a complex with HOXB13 but our data showed that ALX4 inhibited breast cancer metastasis." (PMID 29183346, 2017). "Rare deleterious mutations in highly penetrant genes, such as BRCA2 (breast cancer associated), and HOXB13 (homeobox B13), explain only a small fraction (less than 6%) of the missing heritability." (PMID 29050365, 2017). "HOXB13 was also reported to be involved in other solid tumors, including breast cancer, ovarian cancer, skin cancer, and cervical cancer." (PMID 28808656, 2017). "Breast cancer cells overexpressing HOXB7 or HOXB13 show repression of the estrogen receptor leading to estrogen independence and resistance to tamoxifen." (PMID 27449292, 2016). "We evaluated the entire coding sequence of the HOXB13 gene for germline mutations in 1,250 non-BRCA1/2 breast cancer patients and 800 controls from the Rotterdam Breast Cancer Study (RBCS) study." (PMID 27424772, 2016). "It has been reported that HOXB13 protein mediates tamoxifen resistance and invasiveness in luminal breast cancer by suppressing estrogen receptor (ER) and inducing IL6 protein expression." (PMID 26173622, 2015). "The HOXB13:IL17BR ratio has been reported to predict outcome in early breast cancer patients treated with Tamoxifen, thus we evaluated the predictive value of this ratio in our data set using the same approach as previously reported." (PMID 23342080, 2013). "The Breast Cancer Index (BCI), a gene expression-based signature, is a continuous risk prediction model that combines the gene expression profiles of the HOXB13/IL17BR ratio (H:I) and the Molecular Grade Index (MGI)." (PMID 21999244, 2011). "Immunohistochemical staining of HOXB13 was performed on tissue microarray slides comprising a total of 912 tumors from breast cancer patients." (PMID 20649975, 2010). "The HOXB13:IL17BR index has been identified to predict clinical outcome in the setting of adjuvant tamoxifen monotherapy of breast cancer." (PMID 20649975, 2010). "The expression of HOXB13 is known to be upregulated in breast cancer cells compared with normal breast epithelium and it has also been shown that HOXB13 is an estrogen-regulated gene negatively correlated to estrogen receptor (ER) status." (PMID 20649975, 2010). "Much is known about the function of the homeobox genes in these events, but the role of HOXB13 in breast cancer and endocrine resistance is only beginning to be elucidated." (PMID 20649975, 2010).
breast carcinoma (continued). "In the present study, we used immunohistochemistry to analyze the protein expression of HOXB13 in tumor samples from 912 postmenopausal breast cancer patients." (PMID 20649975, 2010). "The mechanistic effects of HOXB13 in breast cancer are being investigated, but there are few studies published in this matter." (PMID 20649975, 2010). "In breast cancer, HOXB13 also plays an important role in disease progression." (PMID 32546843, 2020). "There were sufficient carriers of HOXB13 p.G84E and p.R217C to allow association analysis in Europeans, however, both mutations did not associate with breast cancer risk." (PMID 32546843, 2020). "In breast cancer, ER and HOXB13 have been shown to regulate each other’s expression." (PMID 32546843, 2020). "Studies indicate that HOXB13 expression level may be useful for identifying appropriate therapeutic regimens in breast cancer." (PMID 29471853, 2018). "The correlation of HBXIP and HOXB13 in ER+ breast cancer was assessed by human tissue microarray." (PMID 29471853, 2018). "Therefore, we conclude that HBXIP can induce TAM resistance by elevating the protein level of HOXB13 in breast cancer." (PMID 29471853, 2018). "Therefore, we comprehensively interrogated the entire HOXB13 coding sequence for mutations in 1,250 non-BRCA1/2 familial breast cancer cases and 800 controls." (PMID 27424772, 2016). "HOXB13 p.Gly84Glu mutation was not contributed to the development of breast cancer (OR = 1.423, 95% CI = 0.774−2.615, P = 0.256) and colorectal cancer (OR = 2.458, 95% CI = 0.98−6.177, P = 0.056) using fixed-effect models." (PMID 26517352, 2015). "However, our estimated 10-year risks of breast cancer death for tamoxifen-treated and untreated patients classified by MGI+HOXB13:IL17BR as low risk (that is, 3.7% and 5.7%) were commensurate to theirs (that is, 2.3% and 5.3%)." (PMID 23497539, 2013). "In breast cancer, HOXB13 was found to be overexpressed in hormone-refractory tumors compared to hormone-responsive tumors, further suggesting that HOXB13 might be a useful prognostic marker for hormone-refractory breast cancers." (PMID 20504375, 2010). "The present study is the first about HOXB13 protein expression in breast cancer." (PMID 20649975, 2010). "Ectopic expression of HOXB13 also enhances migration and invasion in breast cancer cells." (PMID 15928669, 2005). "The results of the current study concur with these observations in that HOXB13 p.G84E does not appear to act as a breast cancer susceptibility allele, neither in overall analyses (OR = 1.035, 95% CI = 0.859–1.246, P = 0.718) nor in analyses enriching for particular (high-risk) subgroups." (PMID 32546843, 2020). "HOXB13 is therefore not a material breast cancer susceptibility gene." (PMID 32546843, 2020). "Thus, although involved in breast cancer progression, HOXB13 is not a material breast cancer susceptibility gene." (PMID 32546843, 2020). "However, we did neither find any association between HOXB13 p.G84E and the risk of breast cancer in any of these high-risk subgroups, nor did we find an association with subtype-specific breast cancer risk." (PMID 32546843, 2020). "Likewise, high-risk subgroup analyses and analyses by receptor status also did not reveal any association between HOXB13 p.R217C and (subtype-specific) breast cancer risk." (PMID 32546843, 2020). "Although in our previous study we found that the HOXB13 p.R217C mutation was 3.5-fold more prevalent in cases than controls, the association between p.R217C and breast cancer risk was not statistically significant and the estimation of the risk was not very precise." (PMID 32546843, 2020). "However, the regulation of HOXB13 in TAM-resistant breast cancer remains largely unexplored." (PMID 29471853, 2018). "Thus, we examined the effect of ASA on the HBXIP/HOXB13 axis in breast cancer." (PMID 29471853, 2018).